GFAP (glial fibrillary acidic protein)
Diseases named in the same sentence as GFAP in open-access papers (continued):
Sharing a sentence is not in itself a finding about the gene and the disease.
autoimmune encephalitis (25 papers, 2018 to 2026). Inflammation of the brain secondary to an immune response triggered by the body itself. "The clinical manifestations of MOGAD and GFAP antibody-associated disorders resemble those of autoimmune encephalitis; thus, autoimmune encephalitis antibody testing can help distinguish them." (PMID 41333477, 2025). "MOGAD and GFAP antibody-associated disorders are easily confused with central nervous system (CNS) infections, autoimmune encephalitis, and metabolic encephalopathy." (PMID 41333477, 2025). "P27 with biallelic STAT1 loss-of-function had glial fibrillary acidic protein (GFAP) autoimmune encephalitis." (PMID 35003119, 2021). "The other three patients with coexisting anti‐CRMP1 and anti‐CRMP2 Abs were diagnosed with autoimmune encephalitis (anti‐GFAP antibody), possible Wernicke encephalopathy, and subacute combined degeneration, respectively." (PMID 40583162, 2025). "Like other autoimmune encephalitis with antibodies against intracellular antigens, the effect of GFAP antibodies is presumed to be mediated via cellular immunity, namely, GFAP-specific CD8+ T-cells." (PMID 39449321, 2024). "Although GFAP-IgG in the CSF was recognized as the fifth most common autoimmune encephalitis biomarker, the role of this antibody in the mechanism of this disease is still obscure." (PMID 36552122, 2022). "The patient tested negative for anti-myelin oligodendrocyte glycoprotein (MOG) antibodies, glial fibrillary acidic protein (GFAP), as well as other autoimmune encephalitis antibodies (anti-GABAB, anti-AMPAR1, anti-AMPAR2, anti-LGI1 and anti-CASPR2)." (PMID 35527314, 2022). "However, there were eight patients with GFAP antibodies occurring simultaneously with clinical and MRI features of autoimmune encephalitis or demyelinating disorders." (PMID 29755396, 2018). "Both NS-AE and IC-AE showed significantly increased densities of GFAP+ astrocytes, neurotoxic astrocytes, and oligodendrocytes compared with NND controls, indicating a common glial response across autoimmune encephalitis subtypes." (PMID 40278930, 2025). "Firstly, the identification of NMDA receptor (NMDAR) antibodies in Patient 1 and GFAP antibodies in Patient 2 underscores the link between SARS‐CoV‐2 infections, CNS invasion, and autoimmune encephalitis." (PMID 38463395, 2024). "Represented in smaller but still significant numbers were other subgroups of autoimmune encephalitis with other antigenic targets including glycine receptor, LGi1, Caspr2, DPPX, GABA-B, IgLON5, GFAP, and SOX1." (PMID 33692738, 2021). "There were three or fewer cases of autoimmune encephalitis with antibodies directed against Caspr2, DPPX, GABABR, IgLON5, GFAP, and SOX1." (PMID 33692738, 2021). "Many of the autoimmune encephalitis subgroups (anti-DPPX, anti-GABABR anti-IgLON5, anti-GFAP, and anti-SOX1) had an antibody present in both serum and CSF in 100% of cases." (PMID 33692738, 2021). "Autoimmune glial fibrillary acidic protein (GFAP) astrocytopathy, a newly defined autoimmune encephalitis, is an antibody-mediated meningoencephalomyelitis." (PMID 31681133, 2019). "Plasma NfL and GFAP ratio of mean values in leucine-rich glioma inactivated 1 autoimmune encephalitis (LGI1 AE) vs. non-inflammatory controls." (PMID 40470500, 2025). "Mean plasma NfL and GFAP levels at symptom onset of Leucine-Rich Glioma Inactivated 1 Autoimmune Encephalitis (LGI AE) compared to non-inflammatory controls." (PMID 40470500, 2025). "Aquaporin-4 (AQP4) antibody, N-methyl-D-aspartate receptor (NMDAR) antibody and GFAP antibody were all positive, whereas the remaining autoimmune encephalitis antibody tests were negative." (PMID 39464885, 2024). "Upon suspicion of autoimmune encephalitis, extensive laboratory testing was performed, and the patient’s serum and cerebrospinal fluid (CSF) tested positive for anti-MOG, while anti-glial fibrillary acidic protein (GFAP) antibodies were detected in her serum." (PMID 39479094, 2024).
autoimmune encephalitis (continued). "The transfection cytology methods were used to detect autoimmune encephalitis antibodies (NMDAR, AMPAR1, AMPAR2, LGI1, CASPR2, GABABR, DPPX, IgLON5, GlyRα1, GABAARα1, GABAARβ3, mGluR1, mGluR5, D2R, Neurexin-3α, GAD65, KLHL11, gAChR, AQP4, MOG, GFAP) in CSF and serum." (PMID 40771880, 2025).
cerebral infarction (25 papers, 2010 to 2025). An ischemic condition of the brain, producing a persistent focal neurological deficit in the area of distribution of the cerebral arteries. "The connection between cerebral infarcts and astrocyte reactivity is well established, and serum GFAP levels have been shown to correlate with severity of acute ischemic stroke and poorer clinical outcomes." (PMID 39580758, 2024). "It has been suggested that the release kinetics of GFAP depend on the presence of a permanent brain infarction." (PMID 38891912, 2024). "Immumofluorescence methods were used to observe the expression of GFAP and Iba-1 in cerebral infarction tissue of MCAO mice." (PMID 35658867, 2022). "Semaglutide treatment reduced the number of CD16/32+ microglia and C3d+/GFAP+ A1 astrocytes and subsequently reduced brain infarct volume, improved neurobehavioral outcomes, reduced neuroinflammation, and attenuated BBB disruption in tMCAO mice." (PMID 35656116, 2022). "Brain injury was assessed in rodents and swine through the following variables: BDNF, brain infarct, GFAP, lesion volume, neurological score and rotarod and were reported in total 4, 19, 4, 7, 15, and 7 studies, respectively." (PMID 30528323, 2019). "In the case of acute CNS injuries like brain infarction and traumatic brain injury, there was increase in levels of GFAP in CSF." (PMID 30526520, 2018). "GFAP−/−Vim−/− mice exhibit larger brain infarcts after middle cerebral artery occlusion suggesting protective role of reactive gliosis after adult focal brain ischemia." (PMID 20442854, 2010). "CHI3L1 ISH signal and immunohistochemistry was co-localized with GFAP staining in all the tested diseases (e.g. AD and brain infarction." (PMID 20540736, 2010). "In the near future, this platform might be a target for treating cerebral infarction after the further improvement of the Rep/Cap packaging plasmid pAAV-PHP.eB with a GFAP promoter." (PMID 39227632, 2024). "In addition, 2 Hz EA reduced Ki67 and nestin immunoreactive cells and increased GFAP immunoreactive cells in ischemia–reperfusion-injured cerebral infarction rats." (PMID 28913350, 2017). "In addition, we studied the effect of secretase inhibitors and caveolin-1 inhibitors on apoptosis, expression of the glial fibrillary acidic protein (GFAP) in astrocytes, and the volume of mouse brain infarction after PTS." (PMID 36289917, 2022). "Compared with the dMCAO group, the Rg1 group exhibited improved neurobehavioral outcomes, reduced brain infarct volumes, enhanced expression of CD31, and increased numbers of BrdU+/CD31+ microvessels and glial fibrillary acidic protein- (GFAP-) positive vessels in the peri-infarct cortex." (PMID 33791075, 2021).
delirium (25 papers, 2014 to 2026). A disorder characterized by confusion; inattentiveness; disorientation; illusions; hallucinations; agitation; and in some instances autonomic nervous system overactivity. "Three studies identify the increased level of GFAP proteins which is significantly associated with delirium in our review." (PMID 39700095, 2024). "Furthermore, in addition to axonal injury, postoperative delirium was also associated with an increase in glial fibrillary acidic protein, a marker of astrocyte activation." (PMID 37576000, 2023). "Additionally, the rise in GFAP, a marker of astrocyte activation, is also associated with postoperative delirium." (PMID 37576000, 2023). "For example, we found plasma GFAP and NEFL levels (biomarkers of neuronal injury) to be associated with incident delirium." (PMID 41286463, 2026). "Irrespective of a COVID-19 infection, serum concentration of MMP-9 and GFAP were significantly higher in delirium." (PMID 39352661, 2025). "Our research adds evidence of elevated NFL and tTau levels in delirium, suggesting that they are more pertinent than GFAP and UCHL-1." (PMID 38566855, 2024). "Practically, serial biomarker ascertainment throughout a delirium episode would need to be blood based, and GFAP and NfL are attractive in this respect." (PMID 39355007, 2024). "Among the unique proteins, we focused on the top 13 most investigated proteins (IL-6, CRP, IL-8, S100B, IL-10, TNF-a, IL-1b, Cortisol, MCP-1, GFAP, IGF-1, IL-1ra, and NFL) that are significantly associated with delirium." (PMID 39700095, 2024). "GFAP has shown increased serum levels in conditions such as septic acute encephalopathy and postoperative delirium." (PMID 38566855, 2024). "This study aimed to investigate the potential correlation between biomarkers of neurofilament light chain and glial fibrillary acidic protein and emergence and postoperative delirium in elderly patients undergoing surgery." (PMID 37576000, 2023). "Although some preoperative studies have reported an association between NfL and delirium, the relationship between GFAP and delirium remains controversial." (PMID 37576000, 2023). "Further research is necessary to explore the role of changes in NfL and GFAP in delirium and their significance as biological markers of delirium." (PMID 37576000, 2023). "Compared with Group C, S100β and GFAP decreased and incidence of postoperative delirium reduced at T3–4 in Group N, the difference was statistically significant (P<.05)." (PMID 28489775, 2017). "In patients with delirium markers of microglial activity (HLA-DR and CD 68), astrocyte activity (GFAP) and IL-6 were increased." (PMID 25943983, 2015). "GFAP may be more useful as a delirium biomarker in the short term, possibly in patients with traumatic brain injury or underlying neurodegeneration." (PMID 41286463, 2026). "In contrast, several studies investigating GFAP as a perioperative biomarker of brain injury found no clear association with delirium." (PMID 39352661, 2025). "One recent study noted increased GFAP levels in delirium patients after undergoing cardiac surgery." (PMID 38566855, 2024). "However, the correlation between GFAP and delirium remains ambiguous, with multiple studies reporting inconsistencies." (PMID 38566855, 2024). "In our study, we found that the changes in NfL and GFAP levels on the 1st day after surgery were still higher in patients with POD than in non-delirium patients, supporting our hypothesis that neuronal axonal injury plays a role in the development of delirium." (PMID 37576000, 2023). "Moreover, there are gaps in the longitudinal analysis of the relationship between NfL, GFAP, and emergence delirium." (PMID 37576000, 2023). "We hypothesised that delirium would be associated with increases in the pro-inflammatory cytokines IL-1β and IFN-γ, and a marker of astrocytosis GFAP, and decreases in anti-inflammatory IGF-1 and IL-1ra, and that this would be shown in the CSF." (PMID 25124807, 2014).
delirium (continued). "Our study observed a significant increase in GFAP levels in delirium patients, suggesting the involvement of astrocyte activation in delirium development, which could be a new target for postoperative delirium therapy." (PMID 37576000, 2023). "In this study, we measured the concentrations of NfL and GFAP in the preoperative and postoperative plasma of elderly patients in order to investigate the relationship between changes in NfL and GFAP during surgery and the occurrence of emergence delirium and postoperative delirium." (PMID 37576000, 2023). "Delirium was assessed using the Confusion Assessment Method for the Intensive Care Unit or Confusion Assessment Method scale, and blood samples were collected before and after surgery for plasma neurofilament light chain and glial fibrillary acidic protein measurements using a single-molecule array." (PMID 37576000, 2023). "Additionally, in patients with postoperative delirium, both the increase in plasma neurofilament light chain protein levels (P < 0.001) and the increase in plasma glial fibrillary acidic protein levels during surgery (P = 0.008) were significantly higher than in non-delirium patients." (PMID 37576000, 2023). "Our observation of increased hippocampal GFAP density provides histological support for this hypothesis in a CPB model, suggesting that the astrocyte activation we observed is a pathological step contributing to the BBB dysfunction associated with postoperative delirium." (PMID 41536627, 2026). "Additionally, exploring the potential of integrating other biomarkers, such as those reflecting neuronal damage (NfL) or astroglial activation (GFAP), along with electrophysiological parameters, could improve prediction and capture the dynamic evolution of delirium." (PMID 41219650, 2025). "Neurofilament-Light chain (NfL) and Glial Fibrillary Acidic Protein (GFAP) are promising blood-based markers for neurodegenerative diseases and potential candidates for delirium." (PMID 40354379, 2025). "We have summarized the 13 most studied proteins (IL-6, CRP, IL-8, S100B, IL-10, TNF-a, IL-1b, Cortisol, MCP-1, GFAP, IGF-1, IL-1ra and NFL) about delirium." (PMID 39700095, 2024). "The most important result reported by the authors was a positive correlation between serum GFAP and UCH-L1 with Intensive Care Delirium Screening Checklist (ICDSC), a practical validated metric which is used to quantify ICU-related delirium." (PMID 36363686, 2022). "Others have shown anti-inflammatory effects of NPD-1 in old mice in a model of postoperative delirium, with reduction of IL-6, TNF-α, glial fibrillary acidic protein (GFAP), and Iba-1 compared with controls." (PMID 34638979, 2021). "However, GFAP’s reliability as a biomarker is less established compared to NFL and tTau in delirium." (PMID 38566855, 2024). "Another study linked both tTau and, to a lesser extent, NFL levels to postoperative delirium severity and recovery, unlike GFAP." (PMID 38566855, 2024). "However, we did not observe significant changes in plasma NfL and GFAP concentrations during general anesthesia surgery in patients without delirium." (PMID 37576000, 2023). "Furthermore, there is no current evidence supporting a link between preoperative GFAP levels and postoperative delirium." (PMID 37576000, 2023). "A recent prospective study on postoperative delirium identified elevated NFL levels but not tTau, GFAP, or UCHL-1 levels." (PMID 38566855, 2024). "Median serum GFAP and CSF SNAP-25 levels were higher in the AD cohort than in non-AD controls, but not in the delirium cohort." (PMID 38566855, 2024). "There were markers in both serum and CSF that differed between the affected and non-affected patients (SCI; IL6, GFAP, CSPG4, delirium; TR4, EZH2, hallucinations; NF1)." (PMID 30367354, 2018).
delirium (continued). "In POD patients, the intraoperative increases in both plasma NfL [non-delirium vs. POD: −0.03 (−0.13–0.06) vs. 0.07 (0.01–0.29), P < 0.001] and GFAP [non-delirium vs. POD: 0.01 (−0.16–0.09) vs. 0.10 (−0.01–0.28), P = 0.008] were significantly higher than in non-delirium patients." (PMID 37576000, 2023).
Encephalopathy (25 papers, 2008 to 2026). Encephalopathy is a term that means brain disease, damage, or malfunction. "In fact, the here identified astroglial Abs turned out to represent GFAP Abs in most cases and were associated with the clinical picture of GFAP encephalopathy." (PMID 40692787, 2025). "The antibodies to GFAP cause inflammations involving the brain, cerebellum, meninges and brain stem, resulting in encephalopathy." (PMID 35624969, 2022). "While GFAP-null mice display minimal phenotype when unperturbed, overexpression of GFAP resulted in a fatal encephalopathy with accumulations of GFAP in Rosenthal fibers." (PMID 40076540, 2025). "The goal of our study was to examine the ability of GFAP to predict grade of encephalopathy and neurological outcome when measured in umbilical cord blood (UCB)." (PMID 26733938, 2015). "Higher Sarnat score (worse encephalopathy) correlated with lower VEGF during the first 24 h of life (DOL 0) and higher tau, GFAP, and IL-10 throughout the first week of life." (PMID 34795631, 2021). "HIV infection without encephalopathy showed a clear increase in GFAP and HLA‐DR immunoreactivity when compared with normal tissues.GFAP and HLA‐DR were not significantly different between HIV and HIVnE groups." (PMID 38282400, 2024). "Serum GFAP concentrations were higher in patients with septic encephalopathy than in septic patients without encephalopathy." (PMID 37744876, 2023). "In a study on 152 patients, the serum concentrations of GFAP in patients with septic encephalopathy were higher than those in patients without encephalopathy." (PMID 37744876, 2023).